TFRC (transferrin receptor)
Diseases named in the same sentence as TFRC in open-access papers (continued):
Sharing a sentence is not in itself a finding about the gene and the disease.
Splenomegaly (7 papers, 2016 to 2025). Abnormal increased size of the spleen. "Erythropoietic expansion as evidenced by the respective markers like soluble transferrin receptors (sTfR), increased nucleated red cells (NRBCs) and growth differentiation factor 15 (GDF-15), will also contribute to splenomegaly leading many clinicians to recommend splenectomy." (PMID 33072976, 2019).
combined immunodeficiency (6 papers, 2017 to 2024). A broad classification of inherited disorders presenting at birth that affect both the cell-mediated and humoral aspects of the immune response. "We herein identified a new disease-causing homozygous germline mutation in the TFRC gene (c.64C > T, p.R22W) (referred to as TfR1R22W from now on) in a Turkish patient with combined immunodeficiency (CID)." (PMID 38270687, 2024). "For example, A missense mutation in TFRC, encoding transferrin receptor 1, causes combined immunodeficiency and TFRC also promotes epithelial ovarian cancer cell proliferation and metastasis via up-regulation of AXIN2 expression." (PMID 35818395, 2022). "Moreover, patients with a rare mutation in transferrin receptor-1 (TfR1), the primary receptor for iron uptake in cells, present with lymphocyte dysfunction and combined immunodeficiency." (PMID 37812650, 2023). "Interestingly, a missense mutation in TFRC, encoding transferrin receptor 1, causes combined immunodeficiency." (PMID 35818395, 2022). "It has been suggested that mutations in the transferrin receptor gene may lead to severe combined immunodeficiency." (PMID 35155543, 2022).
gestational diabetes (6 papers, 2016 to 2025). Carbohydrate intolerance first diagnosed during pregnancy. "Prior works have evidenced an aberrant expression of TFRC in different obstetric complications, such as intrauterine growth restriction, preeclampsia, or gestational diabetes." (PMID 36671505, 2023).
hemorrhagic fever (6 papers, 2009 to 2022). An infectious disease caused by certain viruses or bacteria that can damage the walls of tiny blood vessels, making them leak, and can hamper the blood's ability to clot and cause severe, life-threatening illness. "The ability of a New World (NW) clade B arenavirus to enter cells using human transferrin receptor 1 (TfR1) strictly correlates with its ability to cause hemorrhagic fever." (PMID 19343214, 2009). "One of the groups scanned KFDV virus genome and predicted eight mature miRNAs that regulate two host target genes i.e., ANGPT1 (angiopoietin 1) and TFRC (transferrin receptor) which are involved in hemorrhagic fever and neurological manifestations." (PMID 29868505, 2018).
metastatic cancer (6 papers, 2017 to 2025). A carcinoma which has spread from the original site of growth to another anatomic site. "Antagonizing the NF2-YAP pathway, which promotes ferroptosis by up-regulating modulators like ACSL4 and transferrin receptor (TFRC), offers a new perspective on treating mesenchymal or metastatic cancer cells, which are highly sensitive to ferroptosis." (PMID 38322268, 2024). "As an ideal DOX nanocarrier for our LDNM study, we used H-Ferritin (HFn) nanocages, recently proposed as a promising bionanoparticle for cancer targeting owing to its affinity for transferrin receptor 1 (TfR-1), which is constitutively overexpressed in primary and metastatic cancer cells." (PMID 28039473, 2017). "On the other hand, it has been demonstrated that in EMT or metastatic cancer cells, the activation of YAP1 will up-regulate a variety of irons including acyl-CoA synthase long-chain family member 4 (ACSL 4) and transferrin receptor." (PMID 33996543, 2021). "Using this approach, we intercalated doxorubicin (DOX) into a bifunctional aptamer targeting the transferrin receptor on the BBB and epithelial cell adhesion molecule (EpCAM) on metastatic cancer cells." (PMID 32027209, 2020).
nasopharyngeal carcinoma (6 papers, 2021 to 2025). A carcinoma arising from the nasopharyngeal epithelium. "knocked down TFRC in nasopharyngeal carcinoma, which inhibited the proliferation, migration, invasion and epithelial–mesenchymal transition of nasopharyngeal carcinoma cells." (PMID 40510157, 2025). "We found that tongue squamous cell carcinoma and nasopharyngeal carcinoma cells (including CAL33, CNE-2, S18, and S26) have a similar level of both transferrin (TF) and transferrin receptor (TFRC) genes." (PMID 36012290, 2022). "For example, m6A modification mainly affects RNA stability and protein expression at the post-transcriptional and translational levels in nasopharyngeal carcinoma, but affects post-translational protein modification in HPSCC rather than TFRC stability or mRNA expression." (PMID 34136491, 2021).
preeclampsia (6 papers, 2019 to 2025). Preeclampsia is a hypertensive disorder of pregnancy that is characterized by new-onset hypertension with proteinuria presenting after 20 weeks of gestation, and depending on mild or severe forms may initially present with severe headache, visual disturbances, and hyperreflexia. "Because prematurity, IUGR and preeclampsia have different pathogenic etiologies, the results suggest the importance of further investigation of the epigenetic regulation of TFRC with respect to pregnancy related disorders." (PMID 31253109, 2019). "Interestingly, some predicted target gene products are also associated with preeclampsia, including the transferrin receptor, TFRC." (PMID 34070163, 2021). "TFRC is an essential protein for iron transfer across the placenta and changes in its expression have been associated with IUGR and preeclampsia." (PMID 31253109, 2019). "In parallel, TFRC was shown to be slightly decreased in both types of preeclampsia." (PMID 38790696, 2024). "The level of TFRC mRNA was found to be significantly different in preeclampsia samples in our study, suggesting that TFRC might be regulated under steady-state conditions by hsa-miR-1270 in ECFC." (PMID 34070163, 2021). "TFRC was chosen because it gave the highest score for hsa-miR-1270 on TargetScan and ANGPTL7 was selected because it is related to angiogenesis, and thus has an important link to preeclampsia." (PMID 34070163, 2021). "Since we could not detect any differences in the analysis of NOSTRIN hsa-miR-214-5p between preeclampsia vs. control (NOSTRIN: preeclampsia vs. control: 1.8 × 10−6 vs. 1.0 × 10−6; p = 0.07), we analyzed target genes for hsa-miR-1270 (ANGPTL7 and TFRC)." (PMID 34070163, 2021).
psoriasis (6 papers, 2020 to 2025). An autoimmune condition characterized by red, well-delineated plaques with silvery scales that are usually on the extensor surfaces and scalp. "It has been observed that while the levels of iron and TIBC (Total iron-binding capacity) were significantly lower in psoriasis patients compared to healthy donors, Soluble transferrin receptor (sTfR) and Heme Oxygenase-1 (HO-1) were over-expressed." (PMID 38827737, 2024). "There was a positive association between the Psoriasis Area and Severity Index (PASI) score and three proteins (TFRC, IMPDH2, KRT2)." (PMID 36483564, 2022). "Moreover, in the same conditions, CU-LNA-SLNs reverted to control levels of the increased keratinocyte expression of two markers of ferroptosis, a form of death recently involved in the pathogenesis of psoriasis (TFRC and MDA: 13.4% and 56.1% inhibition, respectively)." (PMID 40005020, 2025). "We observed that the treatment with IMQ-CM induced an increase in the TFRC expression by keratinocytes (33% increase, as compared to control cells, p < 0.05), thus confirming the hypothesis that an increased ferroptosis is involved in the pathogenesis of psoriasis." (PMID 40005020, 2025). "Similarly, the upregulation of PTGS2 and TFRC expression and decreased FTL, GPX4, and FTH1 mRNA levels were observed in psoriasis samples." (PMID 39308857, 2024).
AIDS (5 papers, 2010 to 2024). A syndrome resulting from the acquired deficiency of cellular immunity caused by the human immunodeficiency virus (HIV). "Rapid downregulation of the surface transferrin receptor by oxidative stress represents the physiological mechanism of reduced iron uptake in diverse pathological conditions, including hypoxia-reperfusion injury, acquired immunodeficiency syndrome, and aging." (PMID 35114998, 2022). "HIV infection leads to the chronic activation of B cells, which results in high expression of a protein called the transferrin receptor 1 (TfR1), B-cell dysfunction, and ultimately the development of AIDS-NHL." (PMID 36980702, 2023). "HIV infection leads to the chronic activation of B cells, resulting in high expression of the transferrin receptor 1 (TfR1, also known as CD71), B-cell dysfunction, and ultimately the development of AIDS-NHL." (PMID 36980702, 2023).
colitis (5 papers, 2011 to 2023). Inflammation of the colon. "TFRC has been found to have an anti-inflammatory effect on a murine colitis model." (PMID 32792678, 2020). "However, we observed TFRC disruption caused mild colon injury shown as increased epithelial cell apoptosis but did not change colitis susceptibility." (PMID 36703617, 2023). "To examine the impact of colon injury resulting from TFRC disruption under inflammatory conditions, we treated CDX2ERT2TfrcF/F mice and TfrcF/F mice with dextran sodium sulfate (DSS) to induce colitis." (PMID 36703617, 2023). "Ex vivo binding studies utilizing anti-transferrin receptor immune liposomes have found higher concentrations in the mucosa of rats with DNBS-induced colitis than non-conjugated immunoliposomes." (PMID 33316984, 2020). "The transferrin receptor protein is modestly expressed in healthy tissues but was highly expressed in the basolateral and apical membranes of enterocytes in the colonic mucosa of IBD patients, as well as the colonocytes of rats induced with colitis." (PMID 33316984, 2020).
colon adenocarcinoma (5 papers, 2021 to 2025). "MiR‐141‐3p also modulates the mRNA expression of transferrin receptor via iron‐regulatory protein interplay in two human cell lines, human erythroleukemia K562 cells that have been extensively used for transferrin receptor studies and human colon adenocarcinoma SW480 cells." (PMID 33587339, 2021). "Various potential biomarkers for colon adenocarcinoma initiation and progression and drug targets were identified and discussed, including seven novel markers: ACSL4, ANK2, AMER3, EXOSC1, EXOSC6, GCLM, and TFRC." (PMID 35842572, 2022).
hemorrhage (5 papers, 2019 to 2024). Loss of blood from the vascular compartment to the exterior or into nonvascular body space as a result of rupture or severance of the blood vessels. "Transferrin receptor 1 (TfR1) was correlated with LRNC volume and intraplaque hemorrhage (IPH) volume (R = 0.538, p = 0.017; R = 0.707, p = 0.001)." (PMID 37892018, 2023).
HIV-1 infection (5 papers, 2011 to 2022). The type species of lentivirus and the etiologic agent of acquired immunodeficiency syndrome (AIDS). "Since HIV-1 infection causes generalized immune activation 29, we evaluated cell surface expression of HLA-DR and the transferrin receptor CD71 that represent activated and proliferating T cells." (PMID 22215422, 2012). "The HIV-1 neutralizing activity of nano-curcumin is significantly reduced by antibody to human transferrin receptor in both SUPT1 cells and PBMCs, confirming that the superior ability of nano-curcumin to inhibit HIV-1 infection is dependent on cellular uptake mediated by the transferrin receptor." (PMID 21887247, 2011).
lymph node metastasis (5 papers, 2020 to 2025). "Meanwhile, the expression of TFRC was correlated with pathological stage, lymph node metastasis, malignant degree of cervical lesions and HPV infection status." (PMID 40303995, 2025). "The results indicated a positive correlation between TFRC expression and factors such as pathological stage, lymph node metastasis, and the malignancy level of cervical lesions." (PMID 40303995, 2025). "By analyzing TFRC expression in 105 ESCA tissue samples and correlating these levels with clinical pathological parameters and patient prognosis, we found that higher expression of TFRC was significantly associated with TNM stage, tumor invasion depth, and lymph node metastasis (P < 0.05)." (PMID 40302812, 2025).
sickle cell disease (5 papers, 2012 to 2020). Sickle cell anemias are chronic hemolytic diseases that may induce three types of acute accidents: severe anemia, severe bacterial infections, and ischemic vasoocclusive accidents (VOA) caused by sickle-shaped red blood cells obstructing small blood vessels and capillaries. "The present study investigated the iron stores in patients with sickle cell anaemia by quantifying both serum transferrin receptor (sTfR) and serum ferritin from which the sTFR/log serum ferritin ratio was computed." (PMID 26550015, 2015).
squamous cell carcinoma (5 papers, 2015 to 2025). A carcinoma arising from squamous epithelial cells. "TFRC demonstrated higher expression in adenosquamous compared to squamous cell carcinoma and adenocarcinoma types." (PMID 40046734, 2025). "Conversely, TFRC demonstrated higher expression in adenosquamous compared to squamous cell carcinoma and adenocarcinoma types." (PMID 40046734, 2025). "Given the growing number of studies describing the prognostic value of TFRC in squamous cell carcinomas, we focused our attention on NCBP2 for further assessing effects on cancer aggressiveness." (PMID 36635327, 2023). "NCBP2 and TFRC proteins were primarily expressed in the nuclear and cytoplasmic compartments, respectively, and expression of both proteins was primarily restricted to squamous cell carcinoma cells in the tumour microenvironment." (PMID 36635327, 2023).
ZIKV infection (5 papers, 2020 to 2024). "Studies have shown that ZIKV infection positively regulates the miR-124 expression in neural cells, which leads to a decrease of TFRC, a gene targeted of this miRNA." (PMID 36411728, 2023). "In mouse brain tissue and hNSCs (human neuronal stem cells), ZIKV infection upregulated miR-124-3p and let-7c, which downregulated transferrin receptor (TFRC) and HMGA2 (high-mobility group AT-hook 2) mRNAs, respectively." (PMID 37242305, 2023). "miR-124-3p dysregulates NSC maintenance through repression of the transferrin receptor (TFRC—Transferrin Receptor) in Zika virus infection." (PMID 33233425, 2020). "The allelic and genotypic frequencies of polymorphisms in TFRC and MIR-124-1 were also compared between cases with CZS considering their specific characteristics (sex, ethnicity, trimester of exposure to ZIKV infection and presence of isolated or multiple congenital anomalies)." (PMID 36411728, 2023). "The authors show the transferrin receptor-related mRNA (TRFC) to be a target of this miRNA, and during ZIKV infection it negatively regulates TFRC levels in hNSC-derived neurospheres, resulting in neurosphere size reduction, which may be involved in the microcephaly phenotype." (PMID 36411728, 2023).
acute myocarditis (4 papers, 2021 to 2023). The sudden onset of inflammation of heart muscle with myocellular necrosis; this is generally secondary to an infectious cause, and patients often have a recent history of a flu-like illness. "Further, cardiomyocytes treated with serum from myocarditis patient showed elevated levels of transferrin receptor 1 (TFR1), a receptor for iron import that is upregulated in response to low intracellular iron levels." (PMID 37175422, 2023). "In light of the TFR1 level has been demonstrated significantly increased in acute myocarditis patients and associated with augmented inflammation (CRP, IL-6), we hypothesized that TFRC might be a key effector gene of pro-ferroptosis in CVB3 infection." (PMID 35821227, 2022). "As a dynamic process, CVB3 myocarditis involves complex interactions between viruses and host cells, and whether ferroptosis participates in CVB3-induced myocardial injury and the role of TFRC in CVB3 infection deserve deep in search." (PMID 35821227, 2022).
autoimmune disease (4 papers, 2021 to 2023). A disorder resulting from loss of function or tissue destruction of an organ or multiple organs, arising from humoral or cellular immune responses of the individual to their own tissue constituents. "Iron deficiencies in Treg caused by the depletion of Transferrin receptor 1, a major iron transporter, result in the abrogation of Treg in the intestine and lethal autoimmune disease." (PMID 37188703, 2023). "Decreased cellular iron levels in regulatory T cells via the specific depletion of Transferrin receptor I (TfR1) resulted in lower cellular iron levels and early-onset lethal autoimmune disease." (PMID 37188703, 2023). "A study in 2018 analyzed iron homeostasis parameters (including serum iron, total iron-binding capacity [TIBC], ferritin and soluble transferrin receptor [sTfR]), inflammatory activity parameters, and autoimmune disease parameters between RA patients and healthy controls." (PMID 35958605, 2022).
cardiac hypertrophy (4 papers, 2023 to 2025). "TFRC expression is increased in the pathological cardiac hypertrophy of mice model and positively associated with macrophage infiltration." (PMID 37647427, 2023). "Collectively, these results indicate that TFRC expression is increased in heart tissue with pathological cardiac hypertrophy and positively associated with macrophage infiltration." (PMID 37647427, 2023). "Collectively, these results indicate that TFRC in cardiomyocytes recruits and activates macrophages by secreting Ccl2 in the process of pathological cardiac hypertrophy." (PMID 37647427, 2023). "Moreover, we analyzed the TFRC expression in the heart tissue of mice model with pathological cardiac hypertrophy and found that TFRC protein levels in the HF tissues were significantly higher than those in Control, detected by immunofluorescent staining." (PMID 37647427, 2023). "In this study, our group first explored the role of TFRC in pathological cardiac hypertrophy, and found that TFRC expression in the HF tissue was significantly increased and positively related to macrophage infiltration in the process of HF, indicating that TFRC plays harmful role in HF." (PMID 37647427, 2023). "TFRC in cardiomyocytes recruits and activates macrophages by secreting CCL2 to induce myocardial hypertrophy and promote HF development." (PMID 38034382, 2023). "Furthermore, TFRC in cardiomyocytes recruits and activates macrophages by secreting C‐C motif ligand 2 (Ccl2) in the mice heart tissue with TAC surgery or in the primary cardiomyocytes stimulated with ISO or PHE to induce myocardial hypertrophy in vitro." (PMID 37647427, 2023). "However, whether TFRC is involved in the process of pathological cardiac hypertrophy is not clear." (PMID 37647427, 2023).
chronic myeloid leukemia (4 papers, 2019 to 2021). "Barabas and Faulk have shown that doxorubicin-resistant human chronic myelogenous leukemia cells (K562) and promyelocytic leukemia cells (HL60) have up-regulated transferrin receptor (TfR) expression." (PMID 36046755, 2021). "The transferrin receptor-dependent mechanism is also used for liposomal NABDs internalization, i.e., Mendoça and coworkers have successfully developed a transferrin receptor-targeted liposome loaded with an anti-BCR-ABL siRNA or asODN for the treatment of chronic myeloid leukemia." (PMID 31344836, 2019).
glaucoma (4 papers, 2010 to 2017). Increased pressure in the eyeball due to obstruction of the outflow of aqueous humor. "Endocytosis abnormalities in glaucoma are associated with OPTN mutations, shown to interrupt transferrin receptor recycling and promote autophagic death." (PMID 28575017, 2017). "A glaucoma-associated variant of OPTN, M98K, induces autophagic degradation of transferrin receptor (TFRC) and death in retinal cells." (PMID 26376340, 2015). "However, we lack an understanding of how M98K-OPTN triggers retinal cells to undergo autophagy and degrade TFRC, which could ultimately lead to glaucoma pathology." (PMID 26376340, 2015).